HBB (hemoglobin subunit beta)
Diseases named in the same sentence as HBB in open-access papers (continued):
Sharing a sentence is not in itself a finding about the gene and the disease.
malaria (continued). "The investigation also confirmed other loci previously associated with erythrocyte function and important for protection against malaria such as HBB, ABO, and ATP2B4, and that many of these alleles may have been under balancing selection that predated the human non-human primate split." (PMID 35646724, 2022). "However, HBB variants alone cannot precisely predict the disease as malaria is a complex disease." (PMID 35934714, 2022). "Notably, the potential pathogen-driven selection acting on B4galnt2 in wild mice appears to be similar to the well-documented malaria-driven selection acting on the beta globin gene (HBB) in humans, where one allele confers resistance to a pathogen but carries a cost." (PMID 28806915, 2017). "Current knowledge of the genetic basis of parasitemia levels and IgG levels is reviewed through key examples including the hemoglobinopathies, showing that the protective effect of HBB variants on malaria clinical phenotypes may partially be mediated through parasitemia and cytophilic IgG levels." (PMID 25887595, 2015). "There are extensive reports in the literature regarding selection pressure driven by malaria in the HBB, ABO, DARC and G6PD genes." (PMID 30849090, 2019). "Variants in genes residing in these loci (i.e., HBB, HBA1/HBA2, and G6PD) confer resistance to malaria." (PMID 23696099, 2013). "Variants in genes residing at these three loci (HBB, HBA1/HBA2, and G6PD) confer resistance to malaria in Africans." (PMID 23696099, 2013). "Variations in several host genes (HBB, IL4, IL12, TNF, LTA, NCR3 and FCGR2A) have been reported to be associated with malaria outcome." (PMID 24066864, 2013). "The most striking example is the beta-globin HBB gene, in which three different coding SNPs confer protection against malaria: Glu6Val (HbS), Glu6Lys (HbC), and Glu26Lys (HbE)." (PMID 22957039, 2012). "These include HBB, IL4, TNF, and FCGR2A, which have also been associated with both malaria resistance and IgG levels." (PMID 22947458, 2012). "Allelic-based tests revealed potential associations of HbS polymorphism (rs334, HBB gene), the O blood group (and its components rs8176746 and rs8176719), and rs1126535 (CD40L+220) with severe malaria (P<0.002)." (PMID 22957039, 2012). "The linkage or association of HBB, IL4, IL12, TNF, LTA, and NCR3 with mild malaria or parasitaemia has been previously reported in a population living in Burkina Faso." (PMID 22947458, 2012). "The discovery of a positive selection signal that extends for almost 5 Mb around the cluster of hemoglobin genes (including HBB) in the Taiwan Ami and Atayal may present the first evidence of genetic resistance against malaria." (PMID 24885517, 2014). "HBB, IL4, IL12, TNF, LTA, NCR3 and FCGR2A polymorphisms have been associated with malaria resistance in humans, whereas cytophilic immunoglobulin G (IgG) antibodies are thought to play a critical role in immune protection against asexual blood stages of the parasite." (PMID 22947458, 2012). "Notably, four of the associated loci (ABO, HBB, DARC and CR1) have been implicated in resistance to malaria, a disease endemic in Sardinia until a few decades ago." (PMID 22291609, 2012). "Some genetic variations, such as those found in the hemoglobin subunit beta (HBB), ABO blood group (ABO), ATPase plasma membrane Ca2+ transporting 4 (ATP2B4), glucose-6-phosphate dehydrogenase (G6PD) and CD40 ligand (CD40LG) loci, have been associated with attenuation of severe malaria." (PMID 36895563, 2023). "The presence of a recessive disease causing variant at a high frequency in populations may also due to overdominant selection, i.e., a heterozygous variant provides some advantage to carriers, as is the case for HBB c.20A > T, which provides carriers protection from malaria (MIM:611162)." (PMID 32231685, 2020).
malaria (continued). "HBB and IL18 were enriched in African trypanosomiasis and malaria, respectively, and they were also involved in oxygen transport and the adaptive immune response, as identified in the GO analysis." (PMID 37958518, 2023). "For example, high CrF of HBB and G6PD in Africans can be attributed to malaria resistance." (PMID 40162233, 2025). "With regards to malaria, GWAS have confirmed ABO blood-group association with P. falciparum infection (such as variation at the HBB gene locus), but no novel insights have emerged." (PMID 30405986, 2018). "The frequencies of HBB, G6PD, and NOS2 polymorphisms of children lacking malaria symptoms throughout the year and those showing malaria symptoms were statistically similar." (PMID 28793894, 2017). "This increased the strength of the evidence that HBB, ABO, HBA1-2, and FREM3/GYP are associated with protection against severe malaria compared with the non-weighted case–controls odds-ratios (for HBA1-2: p = 10−5 versus p = 10−4; ABO: p = 10−13 versus p = 10−8; FREM3: p = 10−12 versus p = 10−11)." (PMID 35676275, 2022). "Genes such as HBB and APOL1 have also been reported to have been subject to recent positive selection in Africa by conferring protection against infectious diseases such as Malaria and Trypanosomiasis (sleeping sickness), and APOL1 alleles have also been linked to cardiovascular disease." (PMID 27149122, 2016).
hemoglobinopathies (34 papers, 2011 to 2026). "Hemoglobinopathies due to the HBB mutations encompass a group of clinically distinctive hematological disorders." (PMID 36645044, 2023). "β-Thalassaemia (β-Thal) is caused by mutations in the β-globin gene (HBB), and is one of the most common genetically inherited haemoglobin disorders globally." (PMID 37046464, 2023). "The main purpose of this study is to compare the performance of various in silico predictors and determine the most appropriate ones for predicting the functional impact of short nucleotide variants (SNVs) in HBA1, HBA2, and HBB related to haemoglobinopathies." (PMID 36453528, 2022). "This haemoglobinopathy is caused by mutations, which reduce or eliminate beta globin production from the beta globin gene (HBB)." (PMID 36421683, 2022). "Four of these—coding variants in GCK with diabetes mellitus, LoF variants in HBB with hemoglobinopathies, LoF variants in PKD1 with cystic kidney disease, and coding variants in MIP with cataracts—are novel conditions for population screening." (PMID 34385667, 2021). "Rare variants in HBB cause the recessive hemoglobinopathy β-thalassemia major, which is quite severe and presents early in life." (PMID 34385667, 2021). "Concerning the HBB mutation-specific gene editing strategies for hemoglobinopathies, these have hitherto mostly targeted mutations that create cryptic splice sites that, via aberrant splicing and ensuing coding sequence frameshifts, cause β-thalassemia." (PMID 34713239, 2020). "Mutation study for the HBB gene was conducted for four ß-haemoglobinopathies, HbC [β6; AA Glu→Lys (E→K)], HbD [β121; AA Glu→Gln (E→Q)], HbE [β26; Glu→Lys (E→K)], and HbS [β6; Glu→Val (E→V)]." (PMID 22028795, 2011). "Therefore, an effort was made to identify SNPs that can modify the function and expression of the HBB gene causing hemoglobinopathies and recommend computational strategy for the systematic analysis of SNPs." (PMID 22028795, 2011). "Our in-silico study further suggests the presence of additional deleterious mutations in HBB gene that may affect the structure and function of proteins with apparent roles in hemoglobinopathies and thalassemias." (PMID 22028795, 2011). "In addition to these HBB mutation-independent strategies involving HbF synthesis de-repression, the expanding genome editing toolkit provides increased accuracy to HBB mutation-specific strategies encompassing adult hemoglobin restoration for personalized treatment of hemoglobinopathies." (PMID 34766559, 2021). "It has been reported that between 300,000 to 400,000 children are born with severe hemoglobinopathies each year, and among them 95% are affected with abnormalities of the β-globin gene (HBB)." (PMID 29295702, 2018). "As anticipated, the HBB cluster, BCL11A, and the HBS1L-MYB intergenic region were consistently found to be associated with HbF changes in the included studies across all disease groups (i.e., non-hemoglobinopathy, SCD, β-thalassemia trait), involving a substantial number of SNPs." (PMID 39518961, 2024). "As a result of limited diagnostic potential using high-performance liquid chromatography (HPLC), as it may not detect high oxygen affinity hemoglobinopathies, our NGS panel includes mutations in α- or β-globin genes (HBB, HBA1, HBA2) and the use of HPLC is not part of our algorithm." (PMID 35743463, 2022).
anemia (31 papers, 2014 to 2025). A reduction in the number of red blood cells, the amount of hemoglobin, and/or the volume of packed red blood cells. "β-thalassemia is a widespread anemia of a monogenic hereditary disorder with an autosomal recessive pattern of inheritance that occurs due to mutations in the beta-globin gene (HBB)." (PMID 41202050, 2025). "β-thalassemia results from point mutations or small deletions in the β-globin (HBB) gene that ultimately cause anemia." (PMID 27581487, 2016). "Mutations in the human hemoglobin beta (HBB) gene cause β-thalassemia and those that are homozygous for a given mutation suffer severe anemia." (PMID 26589812, 2015). "We discovered rare deletions in HBA1/HBA2/HBB associated with anemia." (PMID 34764282, 2021). "We discover rare deletions in HBA1/HBA2/HBB associated with anemia." (PMID 34764282, 2021). "The NGS result of a mild anemia participant was αααanti4.2/αα complex HBB c.316-197C>T heterozygous, and her hemoglobin continued to decrease during pregnancy." (PMID 38660679, 2024). "In lung adenocarcinoma, the dysfunction of HBB can directly lead to different degrees of anemia in patients, which has become a major problem in the treatment of lung adenocarcinoma." (PMID 36138770, 2022). "β-Thalassemia (OMIM: 613985) is an inherited hematological disorder caused by mutations of the human hemoglobin beta (HBB) gene, leading to deficient β-globin expression and severe anemia." (PMID 30430274, 2018). "We found down-regulation of HBB in the kidney of infected brown trout, which suggests that erythropoiesis was suppressed in the infected fish, which could generate parasitemia and anemia in brown trout." (PMID 25297457, 2014). "However, there may be considerable variability in hematological phenotype resulting from coexistence with iron deficiency anemia (IDA) and/or coinheritance with alpha thalassemia or delta-globin gene mutations, and presence of silent mutations in HBB gene." (PMID 31941534, 2020).
lung carcinoma (10 papers, 2020 to 2025). "Expression of HBB in lung cancer cells and breast cancer cells is associated with ROS cytotoxicity suppression, leading to cancer cell survival and spread." (PMID 36551747, 2022). "Subsequent studies performed in another lab indicated that HBB regulates the proliferation of lung cancer cells and may serve as a diagnostic biomarker for this malignancy." (PMID 40285526, 2025). "The candidate protein markers were investigated based on the TCGA database, supplemented by Kaplan-Meier plotter and Oncomine analysis, and then AOC3, CLEC3B, CAT, SEPP1, and HBB were selected as potential candidates for early-stage lung cancer." (PMID 40496615, 2025). "A recent study highlighted the pro-tumorigenic role of HBB in lung cancer, supporting our results that HBB promotes proliferation in breast cancer cells." (PMID 40462176, 2025). "Consistent induction of HBB has been observed in single-cell RNA-Seq profiles of circulating tumor cells from breast and lung cancers, suggesting its potential role as a biomarker." (PMID 39495117, 2024). "In our previous study, we identified hemoglobin beta chain (HBB) in the blood plasma of lung cancer patients subjected to chemotherapy, which was related to the presence of HBB in erythrocytes." (PMID 35512017, 2022). "Five of the seven genes (BIRC5, GIMAP5, HBB, IL33, and AKAP12) associated with the LC-LK alignments have been observed to be deregulated in lung cancer." (PMID 36101460, 2022). "The hemoglobin subunit beta was highly expressed in serum of ovarian cancer patients, while tripeptidyl-peptidase 1 was proposed as a biomarker for colorectal and lung cancer." (PMID 32942548, 2020). "The expressions of candidate protein markers were dynamically observed at the various phases of lung carcinogenesis, which revealed that AOC3, CAT, CLEC3B, SEPP1, and HBB may be the key molecular markers of early lung cancer lesions." (PMID 40496615, 2025). "In lung cancer, the five most important mRNAs were HBB, HBA2, MT2A, ZFP36, and DUSP1." (PMID 39495117, 2024). "Moreover, the expressions of CLEC3B and HBB were reduced in the lung cancer group." (PMID 40496615, 2025). "There was a strong correlation between the survival time of individuals with lung cancer and 7 genes (CLEC3B, AOC3, HBB, CAT, SEPP1, FGA, and ORM1, P<0.05)." (PMID 40496615, 2025). "The C-type lectin domain family 3 member B (CLEC3B), membrane primary amine oxidase (AOC3), hemoglobin subunit beta (HBB), catalase (CAT), and selenoprotein P (SEPP1) were screened as candidate protein markers for early-stage lung cancer." (PMID 40496615, 2025). "The candidate protein markers (AOC3, CAT, CLEC3B, SEPP1, HBB) and traditional tumor markers (CEA, CYFRA21-1, NSE) were combined to construct screening models for lung cancer by machine learning techniques." (PMID 40496615, 2025). "A total of 6 genes (LYVE1, CLEC3B, FGA, AOC3, HYDIN, and HBB) exhibited differential expressions in the plasma of LUSC and the area of the lesion in lung cancer (including LUAD and LUSC)." (PMID 40496615, 2025). "Finally, the screening models for lung cancer were constructed by combining candidate protein markers (AOC3, CAT, CLEC3B, SEPP1, HBB) with tumor markers (CEA, CYFRA21-1, NSE) using machine learning." (PMID 40496615, 2025).
breast carcinoma (9 papers, 2016 to 2025). "This study focuses on identifying and validating two genes, PDE3B and HBB, that were implicated in breast cancer progression through an integrative analysis of scRNA-seq, TCGA, and an independent patient cohort." (PMID 40462176, 2025). "This study explores the prognostic and functional roles of PDE3B and HBB in breast cancer, focusing on their contributions to proliferation and immune microenvironment modulation." (PMID 40462176, 2025). "To explore the roles of PDE3B and HBB in breast cancer proliferation, we established overexpression (OE) and knockout (KO) models in MDA-MB-231 cells." (PMID 40462176, 2025). "In summary, our study identifies PDE3B and HBB as key drivers of breast cancer cell proliferation and predictors of poor prognosis." (PMID 40462176, 2025). "The findings not only corroborate previous research on tumor heterogeneity but also provide novel insights into the functional roles of PDE3B and HBB in driving breast cancer progression." (PMID 40462176, 2025). "To further evaluate the role of HBB in breast cancer, we analyzed its protein expression across multiple breast cancer cell lines using Western blotting." (PMID 40462176, 2025). "Our study integrates single-cell RNA-seq, TCGA data analysis, and experimental validation to investigate the roles of PDE3B and HBB in breast cancer proliferation and their potential as prognostic biomarkers." (PMID 40462176, 2025). "HBB protein phosphorylation in S10, S45, and T124 has been identified in breast cancer cells, while the phosphorylation in T5 has been detected in hepatocellular carcinoma and pancreatic ductal adenocarcinoma." (PMID 37569364, 2023). "Extending our observations based on mouse models of metastasis to clinical outcome data, we performed a meta-analysis of HBB expression using multiple publicly available expression datasets containing both primary and metastatic breast cancer samples." (PMID 28181495, 2017). "By combining bioinformatics analysis and experimental validation, this work highlights PDE3B and HBB as potential prognostic biomarkers and therapeutic targets for breast cancer, providing a deeper understanding of the molecular mechanisms underlying tumor heterogeneity and progression." (PMID 40462176, 2025). "This work is most advanced in breast cancer for HBB, although reports are conflicting; HBB has been shown to exhibit some characteristics of a tumour suppressor, while others have shown expression to correlate positively with aggressive cancer behaviours such as proliferation." (PMID 34253873, 2021). "To investigate the relationship between PDE3B and HBB expression and immune infiltration, we utilized EPIC deconvolution to quantify immune cell fractions in TCGA breast cancer samples." (PMID 40462176, 2025). "This analysis identified two genes, PDE3B and HBB, with nonzero coefficients, indicating their potential roles in breast cancer prognosis." (PMID 40462176, 2025). "Furthermore, MTRNR2L12 pseudo‐gene, HBB, and SPDYC were already reported as possible prognostic markers in breast cancer, where their overexpression in tumor cells led to unfavorable prognosis." (PMID 38887841, 2024).
COVID-19 (9 papers, 2021 to 2025). A disease caused by infection with severe acute respiratory syndrome coronavirus 2. "Complement component C3 and hemoglobin subunit beta (HBB) were associated with the immune response to α-Gal in the zebrafish animal model and were both significantly overrepresented in COVID-19 patients when compared to healthy individuals." (PMID 34566994, 2021). "Furthermore, proteomic analysis of airway mucus from severe COVID-19 patients revealed variations in the expression of HBB and HBA1 proteins." (PMID 39358504, 2025). "These proteins either act as positive regulators of cell death (HBG1, HBB, HBD, and HBA1) or are involved in the cellular response to tumor necrosis factor (FABP4, GPD1, THBS1, ASS1, and PCK2), suggesting that apoptosis may be an important cause of heart failure in patients with COVID-19." (PMID 38087340, 2023). "Eight genes associated with platelet activation and pro-thrombosis were upregulated in COVID-19 patients: MPIG6B, HBB, HPSE, CD40LG, STXBP3, CLEC1B, TFPI and GNAS." (PMID 35477940, 2022). "The COVID-19 convalescents had significantly elevated immunoglobulins, Orosomucoid 2 (ORM2), peroxiredoxin-2 (PRDX2), hemoglobin subunits (HBD, HBB and HBA1), as well as proteins involved in cholesterol transport such as cholesteryl ester transfer protein (CETP) and apolipoprotein A1 (APOA1)." (PMID 38396092, 2024). "Among the down-regulated linear RNAs in COVID-19 CSF in our study, HBB (Hemoglobin subunit beta) was not detectable in every COVID-19 CSF samples, while it was expressed in all other CSF samples." (PMID 36759861, 2023). "In comparison, clusters D and E had proteins with higher levels in COVID-19 convalescents, e.g. immunoglobulins playing a role in antigen recognition (e.g. IGKV1-27, IGKV1-39, IGHV1-46, IGLV3-1, and PRDX2), hemoglobin subunits (e.g. HBB, HBA1, and HBD), and carbonic anhydrase (CA1)." (PMID 38396092, 2024).